CCL5 (C-C motif chemokine ligand 5)
Diseases named in the same sentence as CCL5 in open-access papers (continued):
Sharing a sentence is not in itself a finding about the gene and the disease.
cancer (continued). "Additionally, CCL5/CCR5 axis is also a double‐edged sword in cancer." (PMID 33463063, 2021). "Other stromal cell types capable of inducing EMT include cancer-associated fibroblasts employing paracrine TGF-β or IL-32 and Integrin β3–p38 MAPK signaling, mesenchymal stromal cells producing lysyl oxidase, and endothelial cells via PAI-1 (SERPINE1) and CCL5 signaling." (PMID 34063254, 2021). "As these subtypes reportedly differ in survival rate, being the shortest in the MES subtype, and as cancer invasion was found associated with CCL5/CCR5 axis signaling, we hypothesized that CCR5 and/or CCL5 distribution would be significantly different in GB subtypes." (PMID 32545571, 2020). "Collectively, our results are supportive to the hypothesis that the host CCL5 might facilitate cancer cells into evading the host’s antitumor immune responses by suppressing at least the activation status of NK cells, at least in the B16-F10 and YAC-1 metastatic models." (PMID 32218434, 2020). "Therefore, we used ELISA for a subset of leukocyte chemokines ‐ CXCL8 (neutrophils), CCL2 (monocytes) and CCL5 (T‐cells) to determine whether cancer cells or NTF were the main chemokine producers." (PMID 30191960, 2019). "Overexpression of the cancer progression-associated miR-146a in MSC after incubation with exosomes from the MM cell lines RPMI 8226, OPM-2, LP-1, and U266 induces secretion of IL-6, CXCL1, IP-10 (interferon gamma-induced protein 10), and CCL5 and enhances tumor cell survival and migration." (PMID 31281380, 2019). "Thus, high CCL5 serum levels, along with strong IHC (CCL5) staining and poorly- or undifferentiated cancer, may be used to predict peritoneal dissemination and a poorer prognosis." (PMID 29772686, 2018). "An effective reduction in the migratory and invasive ability along with reduction in the secretory levels of CCL5 protein in MAF than CAF was also observed with both the inhibitors, suggesting the possibility to attenuate the crosstalk between MAF and BRCA1 mutated cancer cells." (PMID 30224826, 2018). "We examined whether lactate-activated macrophages can induce cancer cell migration via CCL5." (PMID 29299159, 2017). "Altogether these studies suggest that CCL5/CCR5 signaling regulates angiogenic responses in cancer by modulating certain miRNAs, nevertheless the stimulatory actions mediated by CCR5 may also rely on the direct regulation of the HIF-1α/VEGF transduction pathway." (PMID 29240722, 2017). "Our data suggest that CAF ERα could be applied as a prognostic marker to predict cancer progression, and targeting CCL5 and IL6 may be applied as an alternative therapeutic approach to reduce M2 type macrophages and PCa invasion in PCa patients with low or little ERα expression in CAF cells." (PMID 26790618, 2016). "In this study, our results suggest that CAF ERα could be applied as a prognostic marker to predict cancer progression, and targeting CCL5 and IL6 may be applied as an alternative therapeutic approach to reduce M2 type macrophage and PCa invasion in CAF.ERα(−) PCa patients." (PMID 26790618, 2016). "However, CCL5 was described as a beneficial factor for cancer immunotherapy." (PMID 27329590, 2016). "However, when we examined the mRNA levels and supernatant content of inflammatory cytokines in hUC-MSCs and IL-6-hUC-MSCs, we found that the levels of several cancer-promoting cytokines, including CCL5, PDGF-BB, MCP-1 and TNFα, were markedly downregulated in the IL-6-hUC-MSCs." (PMID 25483835, 2015). "However, bringing this proposal into practical application requires further research to more clearly elucidate the effects of CCL5 on cancer progression and the formation of an immunosuppressive microenvironment to insure that such treatments are supported by the appropriate rationale." (PMID 24523569, 2014). "Thus, it is plausible that CCL2 and/or CCL5 blockade might reduce such immunosuppression and facilitate immunotherapy of HPV associated cancers." (PMID 25340820, 2014).
cancer (continued). "Meanwhile, pan-cancer proteomic analysis showed that CCL5 protein was upregulated in GBM, exhibiting the greatest difference compared to other cancers." (PMID 41155216, 2025). "Cancer cells secrete chemokines like CCL2/MCP-1, CCL5, and CCL8/MCP-2, which recruit TAMs into the TME." (PMID 40361472, 2025). "CCL5 and its receptor CCR5 (C-C chemokine receptor type 5) constitute an axis (CCL5/CCR5) whose role has been extensively studied in cancer progression." (PMID 39827154, 2025). "The heatmap displayed that GPX4 expression was highly correlated with the levels of numerous chemokines and chemokine receptors, such as CXCL16, CCL28, CX3CL1, CCL5, CCR10, CXCR5, and CXCR3, across the majority of cancer types." (PMID 41142608, 2025). "Further analysis of the TCGA BRCA data revealed a positive correlation between CCL5 and LY6E level in cancer tissues." (PMID 40634316, 2025). "In recent years, PARP inhibitors have been described to mediate the release of the two T-cell recruiting chemokines CCL5 and CXCL10 by activating the STING pathway in cancer cells." (PMID 40579444, 2025). "Macrophages are known to recruit T cells via chemokines such as CCL5 and CCL22, and their spatial coupling with lymphocytes in OCRC aligns with studies describing macrophage-driven T-cell chemotaxis in other cancer types." (PMID 41301691, 2025). "Correspondingly, 5 × 2 Gy increased secretion of module 1 (CCL5) and module 4 (CXCL8) chemokines by cancer cells." (PMID 40811032, 2025). "Proteomics results showed that CCL5 and IL18 proteins exhibited the most significant increase in expression in the brain compared to other cancer types." (PMID 41155216, 2025). "The interaction between CCL5 and CCR5 can promote the proliferation and metastasis of cancer cells by enhancing protein kinase B (PKB, AKT) and EMT, while inhibition of the interaction between CCL5 and CCR5 can lead to apoptosis of HCC cells." (PMID 40145607, 2025). "CCR5, CCL5, PDGF-BB, and EphA7 levels, which have been identified in the carcinogenesis of many cancers, were measured in the blood samples using the ELISA method." (PMID 39329983, 2024). "Mechanistically, BCL6 decreases cancer cell expression of pro-inflammatory cytokines and T lymphocyte chemokines such as IL6, IL1F6, and CCL5." (PMID 38956432, 2024). "Here we have evaluated the expression of IGF1, CCL5, IL-8, VCAN and RTN4 in peritumoral AT of women with BC, to investigate their potential role as markers of cancer progression." (PMID 39501160, 2024). "Similar trends were observed in the 3D co-cultures with primary monocyte cells, hMSC and HCT116 cancer cell lines where there was a trend increase in CCL2, CCL5 and GM-CSF in cultures with the hMSCs." (PMID 39310770, 2024). "These CAAs modulate the behavior of cancer cells by releasing proinflammatory mediators such as IL‐6, TNF‐α, CCL2, or CCL5, thereby promoting angiogenesis, proliferation, and metastasis." (PMID 39070181, 2024). "CCL5 secreted from TANs enhances the recruitment of regulatory T (Treg) cells into the TME and promotes cancer cells’ migration and invasion." (PMID 39261943, 2024). "For instance, researchers have utilized a 12-gene expression signature (including CCL2, CCL3, CCL4, CCL5, and others) to assess TLS presence across different cancer types." (PMID 39620224, 2024). "Among chemokines, especially CCL4, CCL5, CCL8, CXCL9, CXCL10 and CXCL11 were markedly positive correlated with LAMP3 expression in most cancers." (PMID 38146591, 2024). "VPS34 inhibition in cancer cells triggers activation of the cGAS–STING pathway and thereby induces a type I interferon response leading to CCL5/CXCL10 chemokine secretion." (PMID 38506049, 2024). "Further analysis showed that inflammatory cytokines (CCL5 and IL-6) derived from the TME are involved in EMT in cancer cells via the STAT3 signaling pathway." (PMID 39126553, 2024).
cancer (continued). "The immunohistochemical analysis revealed significantly higher expression of CD44, MYC, IL17A, CXCL1, FCGR3A, SPP1, and IL1A in cancer tissues, while CXCL12 and CCL5 showed significantly higher expression in adjacent normal tissues." (PMID 39767563, 2024). "In this study, we observed increased macrophage infiltration as well as CCL5, CCL8, and CCL9 expression in AOM/DSS-induced CAC in S100A4Smad4-/- mice, consistent with the pathological changes observed during the inflammation-cancer transition." (PMID 39664586, 2024). "CCL5 and IL17 are also expressed in several solid and hematological malignancies, influencing ECM (extracellular matrix) remodeling and migration, cancer stem cell expansion, DNA damage repair, metabolic reprogramming, and angiogenesis." (PMID 38790160, 2024). "CCL5 is a predictive biomarker of patient response to ICB, as SCLC cancer that expresses high levels of CCL5 presents a hot TME that is associated to a longer overall survival after immune therapy." (PMID 39215193, 2024). "TNF-α induced a significant increase in the secretion of chemokines and cytokines from CT26 cancer cells including CCL2, CCL3, CCL4, CCL5 and G-CSF." (PMID 39310770, 2024). "Using NanoString gene expression technology, we analyzed tumors from mice treated with the VPS34 inhibitor SB02024 and demonstrated that the expression of CCL5 and CXCL10 is increased through a cGAS-STING-dependent mechanism within cancer cells." (PMID 40395527, 2024). "We selected eight candidates (CST4, CCL20, CX3CL1, CXCL5, CXCL8, GDF15, CCL5 and MMP3) that play an important role in cancer pathogenesis for further study." (PMID 38385965, 2024). "In our recent study, we explored the impact and underlying mechanisms of inhibiting the kinase activity of VPS34, a key lipid kinase in the autophagy/endosomal trafficking system, on the expression of CCL5 and CXCL10 in preclinical cancer mouse models." (PMID 40395527, 2024). "Subsequently, homing MSCs secrete CCL5, which binds to CCR5 on cancer cells, inducing the secretion of CSF1 by cancer cells." (PMID 39070181, 2024). "In accordance with the qPCR findings, the WB analyses demonstrated a notable elevation in the protein levels of CCL5, CCR5, and CYP1A1 within the cancer tissues after combination therapy." (PMID 39183447, 2024). "In murine cancer cell lines B16F10 and 4T1, TH1579 treatment at 1 μM for 24 h resulted in increased transcription of Ccl5 and Cxcl10." (PMID 38796460, 2024). "Abnormal expression and activity of CCL5 and its receptor CCR5 have been found in hematological malignancies and solid tumors." (PMID 36983384, 2023). "Carcinogen exposure promotes inflammatory cytokine secretion, including CCL5 and CXCL10, by cancer cells." (PMID 37843274, 2023). "Cancer cells can recruit DCs by releasing chemokines such as CCL4 and CCL5 during the activation of inflammatory signalling pathways under intrinsic stresses including DNA damage." (PMID 37403792, 2023). "PDCD1, TGFB1, CXCL8, CCL3, CCL4, and CCL5 were highly expressed in subTME-IS; CXCL2 and CXCL12 were highly expressed in subTME-ICI, which was consistent among cancer types." (PMID 38002057, 2023). "A variety of metastasis-related chemokines (including CCL5, SDF-1, CCL2, and CCL7) and cytokines (such as IL-1, IL-6, IL-8, and TNF-α) can be released from cancer stem-like cells (CSLCs)." (PMID 36766756, 2023). "The c-Score, derived from expression of CCL4, CCL5, CXCL9, and CXCL10, identified subpopulations of tumors across cancer types with hallmarks of T cell-inflammation." (PMID 37558751, 2023). "One of the chemokines that induce cancer progression via the PI3K/AKT, JAK/STAT3, MAPK/ERK, and NF-κB pathways is CCL-5." (PMID 37736898, 2023). "The elevated expression of CCL2 and CCL5 is mainly secreted by adipocytes, where cancer-derived exosomal miRNA-155 facilitated the production and secretion of CCL2 and CCL5 from adipocytes by modulating the activation of the SOCS6/STAT3 pathway." (PMID 36593475, 2023).
cancer (continued). "This loop promotes the acquisition of cancer stem-like properties and impedes the antitumor efficacy of gemcitabine in PAAD by activating the CCL5/CCR5/Sp1/CD44 axis." (PMID 37553567, 2023). "The cytokines C-C motif chemokine ligand 5 (CCL5) and C-X-C motif chemokine ligand 10 (CXCL10) can induce migration of intratumoral CD8+ T cells in cancer." (PMID 37767098, 2023). "The results of RT-qPCR verified that KU55933 significantly upregulated additional ISGs including ISG20, DDX58, DDX60, CCL5, and IFIT3 in CDDP-R cancer cells." (PMID 37174688, 2023). "Two discovery pan-cancer datasets were used to examine the 4-chemokine signature (CCL4, CCL5, CXCL9, CXCL10; herein referred to as c-Score) as a predictive biomarker for T cell-inflammation and ICI treatment outcomes across different solid tumor types." (PMID 37558751, 2023). "Other IFNγ-induced chemokines CCL5, CCL20, and CXCL1 were shown to be related to cancer progression and poor prognosis." (PMID 37445941, 2023). "There are 28 types of chemokines (CCL1-CCL28) belonging to the CC chemokine subfamily, among which CCL2, CCL3, CCL5, CCL15, CCL18 and CCL26 exert some regulatory effects on pathological processes such as TAMs infiltration and polarization in cancer." (PMID 36173487, 2023). "CCR5 binds with high- affinity to CCL5, CCL3 (MIP-1a), and CCL4 (MIP-1b) in cancer cell membranes to mediate diverse signaling cascades in response to its ligands." (PMID 37553567, 2023). "In a zebrafish model, macrophages increased cancer cell dissemination via CCL2 and CCL5 in the presence of estradiol, which was inhibited with anti-CCL2 and anti-CCL5 treatment, indicating the potential of novel therapies targeting CCL2 and CCL5." (PMID 37208442, 2023). "CCL5 and AREG are critical cytokines that maintain cancer stem-like properties, such as self-renewal, the potential for nondirectional differentiation, and chemotherapy resistance." (PMID 37553567, 2023). "The results showed that high expressions of ISG15, IFI27, OASL, CCL5, ISG20, IFIT3, and other 21 ISGs were significantly correlated with improved OS rates in cancer patients receiving ICB therapy." (PMID 37174688, 2023). "Maraviroc inhibits the binding of CCL5 and CCR5 by reducing the proliferation and metastasis of cancer cells." (PMID 37141250, 2023). "Activated fibroblasts are reported to secrete various growth factors, cytokines such as SDF-1, IL-6, CXCL14, CCL5 and CCL7 and proteases such as MMP-2, MMP-9 and uPA to promote EMT in cancer." (PMID 37065872, 2023). "In addition, MSCs promote the epithelial-to-mesenchymal transformation by secreting CCL5, which promotes the secretion of matrix metalloproteinases that loosen the extracellular matrix in the tumour microenvironment and consequently contribute to cancer cell motility." (PMID 35954425, 2022). "On the other hand, TA-MSCs release CCL5 to bind to CCR5 on breast cancer cells, and then, signal-received cancer cells express CXCL12 to drive the migration and recruitment of TAMs and MDSCs." (PMID 36324128, 2022). "Our experimental approach exploits the paracrine up-regulation of CCL2, CCL5, IL-1β, and IL-6 in ADMSC in response to TNBC cells secretome, confirming and complementing prior co-culture approaches mixing cancer cells and adipocytes." (PMID 35268073, 2022). "CXCL10 and CCL5 are chemokines that induce antitumor immunity in SCLC and other cancer types in response to type I IFNs." (PMID 35584676, 2022).
cancer (continued). "Specifically, we found that DAAM2 was positively correlated with the expression of critical immunomodulators, such as CCL5, CXCL9, and CXCL10, as well as the activities of the cancer-immunity cycle." (PMID 35281277, 2022). "In cancer and inflammatory diseases, the major inflammasome is TNF-α, which activates the NF-κB pathway, whereas the minor inflammasomes are IL-1β, CCL2, and CCL5." (PMID 36139553, 2022). "In this setting, in vitro data suggest that the proliferation of cancer cells harboring CCL5 receptors is related to CD4 T cells, which are the main CCL5 producers among other immune cells." (PMID 36429101, 2022). "Knockdown of NSD1 in head and neck cancer cells resulted in decreased expression of CCL5 and suppressed T-cell infiltration into the tumor microenvironment, suggesting that NSD1 inactivation in cancer has implications for cancer immunotherapy." (PMID 36048239, 2022). "For example, cisplatin triggers the expression of multiple cytokines including IL-6, CCL2, CCL5, CXCL8, BFGF, G-CSF, and VEGF in cancer cells or stromal cells of TME." (PMID 35784460, 2022). "TAMs-derived CCL5 activates STAT3 signaling in cancer cells and increases cell migration, EMT and cell invasion as well as supports cancer stem cell self-renewal." (PMID 36338516, 2022). "Prrx1-induced soluble factors included IL6, CSF, CCL5, and CXCL12, which promote both cancer progression and wound healing." (PMID 35589735, 2022). "The invasion of fat by cancer cells is known to secrete various adipokines such as leptin, adiponectin, IL-6, CCL2, and CCL5." (PMID 35123536, 2022). "This review presents the role of the CCL5/CCR5 axis and its effector mechanisms, and names the most prominent hurdles for the clinical adoption of anti-CCR5 drugs in cancer." (PMID 36430633, 2022). "Certain chemokines, including CCL5 and CXCL12, have further been shown to drive cancer cell metastasis." (PMID 35159113, 2022). "Mechanistically, BAY1082439 converts cancer cell-intrinsic immune-suppression to immune-stimulation by promoting IFNα/IFNγ pathway activation, β2-microglubin expression and CXCL10/CCL5 secretion." (PMID 35013322, 2022). "In other studies, KrasG12D-dependent production of GM-CSF, IL-10, and CCL5, which recruit MDSCs and convert CD4+ T cells to Treg cells, play an important role in cancer progression." (PMID 35127700, 2021). "Logistic regression analysis including the eight cytokines increased in cancer compared to control (GMCSF, IL-1β, IL-6, IL-8, Rantes/CCL5, MIP1α, TNFα, MCP1) was performed." (PMID 35048057, 2021). "Immunohistochemistry results demonstrated that CCL5, CD3E and LCK were expressed at low levels in HCC cancer tissues." (PMID 34218795, 2021). "CCL5 was expressed in cancer cells and lymphocytes, while CCL25 was mainly expressed in cancer cells." (PMID 34771505, 2021). "Several studies reported that CAF-mediated production of CCL5 and MCP1 modulates the cancer environment." (PMID 33923020, 2021). "We selected the eleven cytokines that were significantly increased in cancer (GMCSF, IL-6, IL-1β, Rantes/CCL5, MIP1α, MIP1β, TNFα, MCP1/CCL2, IL-8, IL-12p40, IL10) and selected all the positive Pearson's correlations with r > 0.8 and significance of p < 0.01." (PMID 35048057, 2021). "In multiple dataset validations, CCL5, CXCR6, CD3E and LCK were identified to be down-regulated in cancer tissues." (PMID 34218795, 2021). "Evidence has indicated that Treg cells are recruited to TME through chemokines produced by cancer cells and, in particular, HCC cells have been found to secrete CCL5 and CCL28 chemokines to mediate accumulation of Treg cells." (PMID 35003260, 2021). "CAFs secrete pro-inflammatory cytokines (e.g., COX-2, CXL1, CCL5, CXC11 and IL-6) that induce EMT, cancer cell proliferation, invasion, chemoresistance and inhibit cancer cell apoptosis." (PMID 34830897, 2021).